FURIN (furin, paired basic amino acid cleaving enzyme)
Diseases named in the same sentence as FURIN in open-access papers (continued):
Sharing a sentence is not in itself a finding about the gene and the disease.
tumor (19 papers, 2006 to 2025). "In order to determine the role of FURIN in tumor progression, we evaluated the association of the expression level of FURIN with mutation levels of five MMR genes." (PMID 33968987, 2021). "High expression of the proprotein processing enzyme FURIN has been associated with tumor progression and metastasis." (PMID 26137475, 2015). "In the three neoplasia-derived cells, PC gene expression was also affected, and FURIN was downregulated in all of them." (PMID 39859176, 2025). "We studied the association of rs4702 (FURIN) and rs6603883 (EPHA2) polymorphisms with the classical indicators of NPC prognosis: TNM stage, local tumor invasion (T), lymph node involvement (N), and the presence of metastasis (M)." (PMID 40943407, 2025). "This demonstrates that the role of FURIN in tumorigenesis depends on the particular tumor type and the affected signaling pathways." (PMID 26137475, 2015). "We found significantly increasedexpressions of the PCSK6, PCSK9,MBTPS1, and FURIN genes in tumor tissue,which may indicate the involvement of these PCs in the formation andprogression of esophageal malignancies." (PMID 40264581, 2025). "FURIN knockdown in the BRAF mutant cell line led to reduced tumor growth and increased apoptosis." (PMID 36799665, 2023). "FURIN was differentially expressed in different types of tumor cell lines." (PMID 33968987, 2021). "Furthermore, we analyzed the expression levels of FURIN in 21 tumor cells based on the data of the CCLE database." (PMID 33968987, 2021). "In addition, the TCGA database was applied to evaluate FURIN expression in 20 types of tumors and normal tissues, so as to evaluate the difference of FURIN mRNA levels between normal and tumor tissues." (PMID 33968987, 2021). "To conclude, this study results show that FURIN acts significantly in tumor immunity." (PMID 33968987, 2021). "This study results significantly indicated that FURIN played an essential role in tumor immunity and may act as an important biomarker." (PMID 33968987, 2021). "FURIN inhibition has been proposed as a therapeutic strategy for several tumor types." (PMID 26167473, 2015). "However, the FURIN substrate(s) leading to the early tumor onset is currently unknown and will be part of further investigations." (PMID 26167473, 2015). "Therefore, it has been suggested that inhibition of the ubiquitously expressed proprotein convertase FURIN might be a good therapeutic strategy for several tumor types." (PMID 26167473, 2015). "Thus, when the FURIN expression increases, we found no increased risk for tumor relapse after the surgery." (PMID 26137475, 2015). "Furthermore, Huh7 cells overexpressing FURIN displayed a reduced tumor growth in subcutaneous xenograft experiments, which could be reversed by administration of synthetic FURIN inhibitors." (PMID 26167473, 2015). "Tumor type-specific deviations in ACE2/protease co-expression were less prominent for CTSB, CTSL, and FURIN compared to TMPRSS." (PMID 33707526, 2021). "However, the reduction in or loss of FURIN did not affect the phagocytic abilities of the cells, suggesting that the inhibition of FURIN spares this innate immunity function of macrophages related to the ingestion and degradation of bacteria, dead cells, debris, tumor cells and foreign materials." (PMID 38607027, 2024). "In agreement with the mixed normal and tumor datasets, PBMC displayed positive correlations between ACE2/TMPRSS2, TMPRSS2/FURIN, ACE2/TFRC, FURIN/TFRC, TMPRSS2/CTSL, FURIN/CTSL, TMPRSS2/MYC, and FURIN/AKT1 and a negative association between ACE2/ADAM17." (PMID 33796097, 2021). "Furthermore, isoform structure prediction found that FURIN-001, FURIN-201 and FURIN-202 have the domains P_proprotein, Peptidase_S8, and S8_pro-domain, demonstrating their functional roles in tumorigenesis and SARS-CoV-2 infection in different tumor tissues." (PMID 34671211, 2021). "CTSB, CTSL, and FURIN expression was increased in most tumor types relative to normal tissue." (PMID 33707526, 2021).
tumor (continued). "We subsequently analyzed whether or not the SNP in the FURIN promoter had an impact on FURIN expression in the subset of CRC tumor samples of 688 patients for which gene expression data were also available." (PMID 26137475, 2015). "Therefore, it is not surprising that FURIN is highly expressed in various tumor cell lines and human primary tumors." (PMID 26137475, 2015). "In contrast to patients with CRC where decreased FURIN expression levels do not influence relapse-free survival, we previously demonstrated in a mouse model for pleomorphic adenomas of the salivary glands that even monoallelic deletion of Furin resulted in a significant delay in the tumor formation." (PMID 26137475, 2015). "In any case, it is clear that differences in this SNP in the P1 promoter of FURIN do not affect FURIN expression in CRC and that this SNP has no predictive outcome in this tumor type." (PMID 26137475, 2015).
infection (14 papers, 2020 to 2025). The state of being infected such as from the introduction of a foreign agent such as serum, vaccine, antigenic substance or organism. "While age-dependent variations in ACE2, TMPRSS2, and FURIN expression may influence infection susceptibility and disease manifestation, current evidence remains inconclusive." (PMID 40370452, 2025). "Since SARS-CoV-2 requires the co-expression of proteases TMPRSS2 and/or FURIN for infection, we determined their expression in a subset of patients (n = 38), including all ACE2+ patients (n = 21)." (PMID 36077610, 2022). "Genetic variability within the FURIN gene further modulates infection outcomes." (PMID 41301448, 2025). "Lastly, we observed that infection with H1N1 resulted in prolonged upregulation of the SARS-CoV-2 entry-related genes FURIN and NRP1 that was not linked to viral titres." (PMID 35840680, 2022). "Notably, SARS-CoV-2 Gene Expression Omnibus records of up-regulated genes suggest that coronavirus infection triggers an increased expression of both ACE2 and FURIN genes 4 days after infection." (PMID 35682644, 2022). "Interestingly, our data showed that the additional possibility of priming the SARS‐CoV‐2 S protein by FURIN would potentially render 25% more cells vulnerable for infection as compared to by exclusively TMPRSS2 S protein priming." (PMID 32246845, 2020). "Thereby, the expression of FURIN in only some cells in lung tissue or bronchial branches may have a strong impact on the entire cellular neighborhood, dramatically increasing the likelihood for an infection with SARS‐CoV‐2 of all ACE2+ cells in these tissues." (PMID 32246845, 2020). "Knowledge about the expression of ACE2 and TMPRSS2, as well as other potential entry genes of SARS-CoV-2, namely FURIN, DPP4, and BSG, is extremely important to understand the infection of SARS-CoV-2 and to find ways to prevent the infection." (PMID 33081421, 2020). "Although previous studies have identified certain polymorphisms in the ACE2, ADAM17, FURIN, IFITM3, and VDR genes associated with infection susceptibility to SARS-CoV-2, our findings did not reveal any such associations (data not shown)." (PMID 40296872, 2025). "It is worth investigating whether these clinical manifestations are due to a non-reproductive infection of T lymphocytes, exploiting the proprotein convertase FURIN." (PMID 34356057, 2021). "Importantly, P. aeruginosa infection increased TMPRSS2 mRNA expression over time in CF but not in non-CF primary hAECs, whereas the infection did not affect ACE2 and FURIN expression." (PMID 34950129, 2021).
cardiovascular disease (4 papers, 2020 to 2024). "In addition, cis-pQTLs for FURIN were associated with lipids, blood pressure, and cardiovascular disease (CVD)." (PMID 39406990, 2024).
infectious disease (4 papers, 2021 to 2024). A disorder directly resulting from the presence and activity of a microbial, viral, or parasitic agent in humans. "There are more than 80 compounds identified targeting FURIN, most developed as inhibitors targeting FURIN function in infectious diseases." (PMID 36207451, 2022).
neurological diseases of the (1 paper, 2022). "FURIN is necessary for axonal growth and development of dendritic arbors, a process linked to neurological diseases of the CNS." (PMID 36386965, 2022).
FURIN also shares sentences with these, for which no sentence is quoted: Cognitive impairment (3 papers); depression (3); metabolic syndrome (3); preeclampsia (3); bipolar disorder (2); ovarian carcinoma (2); psychiatric disorder (2); Sjögren's syndrome (2); skin cancer (2); thyroid cancer (2); adrenocortical tumors (1); allergic asthma (1); allergic disease (1); Alzheimer disease (1); amyotrophic lateral sclerosis (1); angina (1); aorta (1); arteriosclerosis (1); atopic dermatitis (1); attention deficit-hyperactivity disorder (1); autism spectrum disorder (1); autoimmune disease (1); behavioral disorder (1); bladder urothelial carcinoma (1); breast carcinoma (1); cholera (1); colon adenocarcinoma (1); epilepsy (1); essential hypertension (1); fatty liver disease (1).
A further 31 diseases each share a sentence with FURIN in 1 paper.